RFPL1S (RFPL1 antisense RNA 1)
Synonyms: RFPL1-AS; NCRNA00006; LOC102723305; formerly RFPL1-AS1
Gene: Long non-coding RNA gene on chromosome 22 (29,409,067 to 29,478,923, reverse strand). Ensembl gene ENSG00000225465.
Diseases named in the same sentence as RFPL1S in open-access papers:
RFPL1S is named in the same sentence as 3 diseases in open-access papers, as found by Europe PMC text mining. Sharing a sentence is not in itself a finding about the gene and the disease. The quoted sentences say what the papers report.
breast carcinoma (1 paper, 2025). "Comparison of the lncRNA expression profile in premenopausal fibroids (GSE224991) with estrogen-regulated lncRNAs identified in breast cancer revealed several overlapping transcripts, including MIR503HG, LINC00511, RFPL1S, and CTB-178M22.2, which were upregulated in both datasets." (PMID 40725045, 2025).
tumor (4 papers, 2019 to 2025). "lncRNAs such as DIO3OS, EMX2OS, KCNQ1DN, KCNQ1OT1, LOH12CR2, and RFPL1S have been shown to associate with a negative gene signature, which links lncRNA to tumor suppression mechanisms." (PMID 41300873, 2025). "Of these lncRNAs, six were common to tumor cells, RFPL1S (p = 0.019), PPP1R26-AS1 (p = 0.008), RP11-439E19.3 (p = 0.01), CASC15 (p = 5.27 × 10–5), AC004540.5 (p = 0.00042), and CTD-2881E23.2 (p = 8.4 × 10–6), while two were unique to DTCs, ZRANB2-AS2 (p = 0.033) and LINC00511 (p = 0.03)." (PMID 31920530, 2019). "They reported up-regulation of RFPL1S, PPP1R26-AS1, RP11-439E19.3, CASC15, AC004540.5, and CTD-2881E23.2 while down-regulation of USP3-AS1, CHRM3-AS2 and RP6-99M1.2 in tumor cells compared with the corresponding non-tumor mononuclear cells isolated from bone marrow (MNCs)." (PMID 33718173, 2021). "On the basis of the principle of ceRNA hypothesis, C22orf34, RFPL1S, and LINC00996 shared same expression patterns as CXCL10, CXCL9, CCL5, FCGR3A, and CCR2, all which were upregulated in tumor tissues of PTC with HT compared with those without HT." (PMID 36266640, 2022).
RFPL1S also shares sentences with these, for which no sentence is quoted: colorectal cancer (1 paper).